PVR (PVR cell adhesion molecule)
Diseases named in the same sentence as PVR in open-access papers (continued):
Sharing a sentence is not in itself a finding about the gene and the disease.
neuroblastoma (11 papers, 2013 to 2025). Neuroblastoma (NB) is the most common solid, extracranial childhood tumor. "Castriconi and others evaluated the cytotoxic effects of NK cells on freshly-isolated neuroblastoma cells and discovered that susceptibility to NK-mediated lysis correlated with the poliovirus receptor (PVR/CD155)." (PMID 26729169, 2015). "Additionally, PVR has been shown to critically determine NK cell-mediated cytotoxicity of neuroblastoma cells." (PMID 35326601, 2022). "While there are no current clinical trials that investigate the blocking of the PVR-TIGIT axis in neuroblastoma yet, it could be a promising approach, particularly in combination with the already established anti-GD2 immunotherapy or with GD2-specific CAR T cell strategies." (PMID 39860532, 2025). "Blocking the PVR-TIGIT axis has demonstrated enhanced anti-tumor immune responses across various cancer types, and preclinical data suggest that targeting this pathway could also improve immune responses in neuroblastoma." (PMID 39860532, 2025). "As such, upregulation of PVR in MYCN-non-amplified SH-SY5Y neuroblastoma cells by PBNP-PTT-administered thermal doses may enable increased NK cell-mediated tumor clearance." (PMID 35326601, 2022).
poliovirus infection (10 papers, 2004 to 2025). An disease or disorder caused by infection with Enterovirus C. "TICAM-1−/− and human PVR—transgenic mice were more susceptible to poliovirus infection than the wild-type and MAVS−/− transgenic mice." (PMID 39335111, 2024). "Mice become susceptible to poliovirus infection after transgenic (tg) expression of the human PVR." (PMID 31924205, 2020). "Therefore, the PVR is required to establish in vivo infection, although its expression does not in itself determine whether specific cell types are susceptible to poliovirus infection; other factors such as innate immune responses play a role." (PMID 31924205, 2020). "This is supported by the well-known fact that poliovirus infection typically occurs only in human and primate cells, whereas it can also replicate in rat cells expressing human PVR." (PMID 39335111, 2024). "Poliovirus receptor (PVR/CD155) was initially identified as a receptor that mediated poliovirus infection." (PMID 35384345, 2022). "Poliovirus infection begins with the attachment of the virus its receptor CD155/PVR." (PMID 28166307, 2017).
triple-negative breast carcinoma (10 papers, 2020 to 2025). An invasive breast carcinoma which is negative for expression of estrogen receptor (ER), progesterone receptor (PR), and human epidermal growth factor receptor 2 (HER2). "For triple-negative breast cancer, high PVR expression is a feature of tumor cells with the mesenchymal phenotype." (PMID 39335111, 2024). "Immune-checkpoint (IC) modulators like the poliovirus receptor (PVR) and programmed death ligand 1 (PD-L1) attenuate innate and adaptive immune responses and are potential therapeutic targets for diverse malignancies, including triple-negative breast cancer (TNBC)." (PMID 37230983, 2023).
acute myeloid leukemia (9 papers, 2018 to 2025). Acute myeloid leukemia (AML) is a group of neoplasms arising from precursor cells committed to the myeloid cell-line differentiation. "In this investigation we show that acute myeloid leukemia (AML) cell lines and AML patient samples highly express the T-cell immunoreceptor with Ig and ITIM domains (TIGIT) ligands PVR and PVRL2." (PMID 29855615, 2018). "In a study of hematologic malignancies, high PVR expression was identified as an independent negative prognostic marker for survival in patients with acute myeloid leukemia (AML)." (PMID 35625835, 2022).
endometrial cancer (8 papers, 2016 to 2024). Primary or metastatic malignant neoplasm involving the endometrium (mucous membrane that lines the endometrial cavity). "It has also been reported that cancer-associated fibroblasts derived from endometrial cancer have decreased PVR expression and more substantial suppression of the cytotoxic activity of NK cells." (PMID 39156900, 2024). "Analysis using TCGA data shows that both PVRL2 and PVR are highly expressed in endometrial cancer, but PVRL2 expression is more predominant." (PMID 39156900, 2024). "CAFs isolated from endometrial cancer tissue inhibit NK cell-mediated cell death through downregulation of the ligand poliovirus receptor (PVR/CD155), which activates the NK cell receptor DNAM-1, thereby aiding cancer progression." (PMID 36797782, 2023). "Along similar lines, CAFs isolated from patients with endometrial cancer have been shown to potently suppress NK cell activity along with the downregulation of PVR cell adhesion molecule (PVR), yet another NK cell-activating receptor." (PMID 36319998, 2022). "PVRL2 and PVR are highly expressed in ovarian and endometrial cancers." (PMID 39156900, 2024). "CAF isolated from endometrial cancer have the ability to reduce NK cell activation by downregulating the ligand of DNAM1, the poliovirus receptor PVR/CD155, on their surface." (PMID 35892828, 2022). "Notably, gynecological cancers such as ovarian and endometrial cancers exhibit high expression levels of PVRL2 and PVR, with similar trends observed in various other solid and hematologic tumors." (PMID 39156900, 2024). "Furthermore, in endometrial cancer, CAFs can decrease NK cells’ lytic potential through their downregulation of poliovirus receptor (PVR/CD155), a ligand of the activating DNAM-1/CD226." (PMID 36338519, 2022).
HIV-1 infection (8 papers, 2016 to 2025). The type species of lentivirus and the etiologic agent of acquired immunodeficiency syndrome (AIDS). "Upregulation of PVR can occur on CD4+ T cells in HIV-1 infection, especially on lymph node TFH CD4+ T cells, which are the major site of HIV-1 reservoir concentration." (PMID 32432050, 2020). "Additionally, PVR/CD155 appears to play a role in NK cell immunity in HIV-1 infection, in which downregulation of the receptor on infected CD4+ target T cells, a process mediated by the viral Nef protein, leads to increased antiviral activity among KIR2DL5-positive NK cells." (PMID 38149259, 2023). "Secondly, there is evidence that HIV-1 infection of CD4+ T cells induces upregulation of PVR expression and that the latent HIV reservoir is to some extent concentrated in CD4+ T cells expressing PVR and/or TIGIT." (PMID 32432050, 2020). "As NK cell and CD8+ T cell expression of TIGIT increases with acute HIV-1 infection, introducing mAb therapy to overcome the higher affinity TIGIT/PVR inhibitory interaction in favor of DNAM-1/PVR-mediated activation is a rational strategy to address lingering HIV-1 infection." (PMID 32432050, 2020). "Our observation that Vpu preferentially targets BST-2 over other TM proteins (NTB-A, PVR, and CD62L) upon IFN treatment raises the possibility that the polyfunctionality of Vpu could be reduced during acute HIV-1 infection." (PMID 31213558, 2019). "Conceivably, the impact of HIV-1 proteins on PVR expression can be overlooked in experimental cell systems in which T cell activation, a prerequisite for permissive HIV-1 in vitro replication as well as a cause of PVR upregulation, is induced before rather than after HIV-1 infection." (PMID 31366013, 2019).
medulloblastoma (8 papers, 2013 to 2025). A malignant, invasive embryonal neoplasm arising from the cerebellum. "We further assessed the association of CD276, CD47, CD24, and PVR expression profiles by nCounter and patient survival analysis in the 80 medulloblastomas Brazilian cohort." (PMID 36825029, 2023). "While medulloblastoma target cells expressed the NK cell ligands PVR and MIC A/B, they also express HLA class I." (PMID 31547819, 2019). "Therefore, additional studies are warranted to clarify the PVR role in medulloblastoma’s biology and therapy." (PMID 36825029, 2023). "Indeed, several groups demonstrated elevated levels of PVR/CD155 in medulloblastoma." (PMID 39335111, 2024). "Among the 19 immune checkpoint-related genes evaluated by nCounter in the Brazilian series of medulloblastomas, we found increased mRNA counts of CD24, CD276, CD47, and PVR (CD155)." (PMID 36825029, 2023).
osteosarcoma (7 papers, 2020 to 2025). A usually aggressive malignant bone-forming mesenchymal neoplasm, predominantly affecting adolescents and young adults. "The expression of PVRL2 and PVR by osteosarcoma cell lines add more complexity to the TIGIT/CD226 signaling network." (PMID 38791381, 2024). "As a target tumor model, we used the osteosarcoma cell line Saos2/143 that naturally express the ligands for TIGIT (CD155/PVR) but also other inhibitory receptors, such as PD-L1." (PMID 34112738, 2021). "Osteosarcomas have been previously shown to express CD155 (Poliovirus Receptor, PVR), which is one of the ligands for DNAX accessory molecule-1 (DNAM-1 or CD226), an activating receptor expressed on NK cells, monocytes and a subset of T cells." (PMID 32082316, 2020).
bladder cancer (6 papers, 2019 to 2026). "In a nutshell, we employed data from three independent cohorts in open database, and our own cohort to explore the expression and mutation profile of PVR (CD155) in bladder cancer." (PMID 34150627, 2021). "Besides, BLCA samples with higher WHO grade or higher pathologic stage tended to express higher level of PVR, highly suggesting that PVR was associated with the progression and malignancy of bladder cancer." (PMID 34150627, 2021). "First, we evaluated PVR expression levels in various common cancer types including bladder cancer, and found that tumor samples demonstrated significantly up-regulated PVR expression compared to normal bladder tissues, suggesting an association with bladder cancer development." (PMID 34150627, 2021). "Based on the median values of PVR expression in bladder cancers, samples were divided in to PVRlow and PVRhigh subgroups for subsequent Kaplan-Meier survival analysis." (PMID 34150627, 2021). "Positively correlated with stromal, immune, and ESTIMATE scores, PVR mRNA expression level demonstrated a significant opposite trend to purity in bladder cancer." (PMID 34150627, 2021). "We herein conducted a comprehensive analysis based on several independent cohorts from open databases, plus our own cohort to explore the profile of PVR in bladder cancer in order to better understand its biological functions there." (PMID 34150627, 2021). "In this report, we assessed the profile of PVR, and found that PVR expression was increased in various cancer types including bladder cancer." (PMID 34150627, 2021). "We obtained data from publicly available databases (TCGA BLCA, n = 408; GSE13507, n = 165; GSE32894, n = 224) to evaluate the mRNA expression levels of PVR in bladder cancer." (PMID 34150627, 2021). "We employed comprehensive bioinformatic analyses to elucidate that PVR is definitely a critical molecule and helps clinicians to optimize a novel approach to the management of bladder cancer, especially MIBC." (PMID 34150627, 2021). "PVR was overexpressed across various cancers including bladder cancer and related to poorer overall survival in bladder urothelial carcinoma (BLCA)." (PMID 34150627, 2021). "Subsequent stratification analysis demonstrated higher PVR expression in higher WHO grade and higher stage in two data sets, indicating the potential role of PVR in governing the malignancy properties of bladder cancer." (PMID 34150627, 2021). "Obviously, further work will be necessary in order to assess whether PVR exerts such functions in bladder cancer." (PMID 34150627, 2021). "Our study revealed that PVR was overexpressed and related to poor prognosis in bladder cancer." (PMID 34150627, 2021). "We next used our Xiangya cohort to investigate whether PVR correlates with immune infiltration and tumor purity within bladder cancer." (PMID 34150627, 2021). "Further analysis showed that increased PVR mRNA expression was related to poorer overall survival in multiple cancers including BLCA, re-analysis in two independent GEO cohorts also identified PVR as a significant risk factor in bladder cancer." (PMID 34150627, 2021). "However, current studies seldom clarify the role of PVR in primary bladder cancer." (PMID 34150627, 2021). "Therefore, we supposed that PVR could mediate similar immune functions in bladder cancer." (PMID 34150627, 2021).
esophageal cancer (6 papers, 2020 to 2025). A primary or metastatic malignant neoplasm involving the esophagus. "In another study, esophageal cancer patients in the PVR-positive group showed unfavorable survival compared to those in the PVR-negative group." (PMID 35625835, 2022).
non-small cell lung carcinoma (6 papers, 2020 to 2024). A group of at least three distinct histological types of lung cancer, including non-small cell squamous cell carcinoma, adenocarcinoma, and large cell carcinoma. "A previous investigation discovered that PVR is a potential predictor or marker of anti-CTLA4 immune response in non-small cell lung cancer." (PMID 37266661, 2023).
prostate carcinoma (6 papers, 2004 to 2025). A carcinoma that arises from epithelial cells of the prostate gland. "PVR is highly expressed in many cancers, including prostate cancer, and its high expression is associated with poor clinical outcomes for prostate cancer patients." (PMID 33343635, 2020). "Our finding of a PVR enhancer is the first report indicating the potential role of PVR in prostate cancer." (PMID 33343635, 2020). "Among the enhancers, a critical enhancer of the PVR gene was investigated in prostate cancer owing to its potential regulatory role in mediating immune repression." (PMID 33343635, 2020). "We generated a clinical dataset based on prostate cancer patients who had accepted androgen ablation therapy, and we found a significant decrease in PVR expression in patients after treatment." (PMID 33343635, 2020). "In support of our proposition, a reanalysis of AR binding with an AR ChIP-seq dataset containing both normal and tumor samples of prostate cancer revealed that AR binds only to the PVR enhancer region in the prostate tumor samples but not in the normal prostate tissue." (PMID 33343635, 2020).
autoimmune disease (5 papers, 2016 to 2023). A disorder resulting from loss of function or tissue destruction of an organ or multiple organs, arising from humoral or cellular immune responses of the individual to their own tissue constituents. "For example, PVR, also known as CD155, involves in the regulation of T-cell activation and is associated with autoimmune diseases such as type 1 diabetes (T1D), had two SNPs showing AEI for ductal cells in Fadista." (PMID 33661921, 2021). "The PVR/TIGIT/CD226/CD96 signalling axis represents a promising therapeutic target for both cancer immunotherapy and the treatment of autoimmune diseases." (PMID 36944702, 2023). "PICALM, PVRL2, PVR, and CLU have shown to be related to systemic, an autoimmune disease characterized by vascular injury and debilitating tissue fibrosis." (PMID 30666269, 2018).
poliomyelitis (5 papers, 2011 to 2016). An acute infectious disorder that affects the nervous system. "For example, the Ala67Thr mutation in the poliovirus receptor gene (PVR) was previously associated with a higher risk for developing vaccine-induced and wild-type virus-induced poliomyelitis." (PMID 24945853, 2014). "Mice transgenic for the human PVR (Tg-PVR) were produced to create a convenient animal model that develops poliomyelitis following PV inoculation by various routes." (PMID 21994791, 2011). "More recently, Shimizu’s group hinted at the existence, in feces of poliomyelitis cases, poliovirus strains that do not bind the poliovirus receptor (PVR)." (PMID 26771630, 2016).
colon adenocarcinoma (4 papers, 2021 to 2024). "Therefore, in order to assess the antitumoral functions of NK cells derived from CRC pts, we performed a degranulation assay against the classical target cells of NK cells, K562 and human colon adenocarcinoma cell line (Caco-2), both expressing PVR and Nectin-2." (PMID 39126041, 2024).
lung squamous cell carcinoma (4 papers, 2021 to 2025). "We analyzed the expression of PVR and programmed death ligand-1 (PD-L1) in surgically resected squamous cell lung carcinoma (SQCC) and determined its prognostic significance." (PMID 33879814, 2021). "In conjunction with the survival curves drawn using TCGA data of lung squamous cell carcinoma, we analyzed the median recurrence-free survival (mRFS) and median OS (mOS) of patients according to high or low expression levels of PD-L1 (CD274) and PVR." (PMID 33879814, 2021).
myeloid leukemia (4 papers, 2020 to 2024). A clonal proliferation of myeloid cells and their precursors in the bone marrow, peripheral blood, and spleen. "DNAM1 blockade did very little in any of our assays, in opposition to previous reports showing DNAM-1 activation of NK cells via interaction with CD112 (Nectin-2) and CD155 (PVR) on myeloid leukemias." (PMID 35222407, 2022).
colorectal tumor (3 papers, 2018 to 2025). "Anti-TIGIT antibody and recombinant mouse PVR protein were used to treat the colorectal tumor CT26 bearing mice." (PMID 30555485, 2018).
gallbladder cancer (3 papers, 2021 to 2025). "The single-cell immune microenvironment reveals that ASPH not only enhances the expression of immune checkpoints, namely PDL1 and PVR, in the gallbladder cancer epithelium, resulting in immune evasion, but also triggers epithelial-mesenchymal transition and migration, promoting metastasis." (PMID 40110547, 2025).
liver cancer (3 papers, 2022 to 2025). An epithelial or non-epithelial malignant neoplasm that arises from the liver. "Wang designed a novel polymerized nanoparticle that targets lncRNA INK4 as well as T cell immune receptors with Ig and ITIM domains (TIGIT)/poliovirus receptors (PVR) to inhibit liver cancer." (PMID 36968595, 2023).
pancreatic adenocarcinoma (3 papers, 2021 to 2023). "On the contrary, increased PVR expression was associated with the better prognosis in pancreatic adenocarcinoma (PAAD; HR = 0.74, 95% CI = 0.56-0.98, p = 0.039)." (PMID 34150627, 2021).
squamous cell carcinoma (3 papers, 2007 to 2025). A carcinoma arising from squamous epithelial cells. "We observed higher expression of immune checkpoint ligands (PVR, NECTIN2, CD274, CD80, and CD86) in the tumor cells at the invasive front of the squamous cell carcinomas." (PMID 41309580, 2025).
acute leukemia (2 papers, 2019 to 2021). A clonal (malignant) hematopoietic disorder with an acute onset, affecting the bone marrow and the peripheral blood. "Among them, DNAX accessory molecule 1 (DNAM-1) recognizes the poliovirus receptor (PVR) and nectin-2 expressed on various acute leukemias by inducing antitumor activity." (PMID 34206399, 2021). "Relevant for antileukemia activity, DNAX accessory molecule 1 (DNAM-1) (CD226) can recognize the specific ligands poliovirus receptor (PVR) (CD155) and Nectin-2 (CD112), found to be expressed on various acute leukemias." (PMID 31623224, 2019).